Y_RNA (Y RNA )
Gene: Miscellaneous RNA gene on chromosome 6 (10,674,658 to 10,674,768, reverse strand). Ensembl gene ENSG00000201048.
Homologues: Orthologues: chimpanzee Y_RNA (97% identical), macaque Y_RNA (92% identical), rat Y_RNA (59% identical). Paralogues in human: RNY1 (87% identical), Y_RNA (85% identical), Y_RNA (84% identical), Y_RNA (83% identical), Y_RNA (82% identical), Y_RNA (81% identical), RNY1P11 (80% identical), Y_RNA (80% identical), Y_RNA (79% identical), RNY1P8 (78% identical), Y_RNA (78% identical), Y_RNA (77% identical), and 96 more.